IL10 (interleukin 10)
Diseases named in the same sentence as IL10 in open-access papers (continued):
Sharing a sentence is not in itself a finding about the gene and the disease.
colitis (continued). "Together, a deregulated immune phenotype (low IL-10 and high IL-12p40) of PI3KδD910A B cells appears to contribute to the pathogenesis of T cell-mediated colitis." (PMID 31546615, 2019). "Similar increases in IL-10+Tregs have been reported by other groups also, where they demonstrated the therapeutic potential of cystatins from other helminth parasites in colitis." (PMID 31683524, 2019). "For example, one study found that occurrence of colitis was substantially increased in SPF IL10−/− mice administered with repeated oral gavage of A. muciniphila." (PMID 30828386, 2019). "Cell death was suggested to be a driver of colitis and overexpression of the pro-survival protein Bcl-2 in intestinal epithelial cells ameliorated chronic inflammation in an interleukin-10 (IL-10) knockout mouse model." (PMID 31877961, 2019). "Even when IL-10−/− mice spontaneously develop a colitis, sharing features with colonic IBD, various studies have support that the enterocolitis of these mice represents a model of CD." (PMID 31608070, 2019). "B. adolescentis IF1-11 showed weak protection ability for proinflammatory factor increments, with increased TNF-α and decreased IL-10 secretion by the colonic lamina propria compared to the DSS-colitis model." (PMID 30987344, 2019). "On the other hand, BGF dramatically elevated the level of IL-10 in colitis mice in a dose-dependent manner compared to the DSS model group (p < 0.01)." (PMID 32116661, 2019). "In a dextran sulfate sodium-induced colitis model, oral administration of fungal chitin reduced the inflammatory parameters and leukocyte infiltration into the gut mucosa and increased IL-10 production via stimulation of NOD-2 and TLR8." (PMID 31781518, 2019). "Emulsifiers promote colitis in IL-10-/- mice by increasing inflammatory markers such as fecal lipocalin-2 or myeloperoxidase activity." (PMID 31109097, 2019). "According to the results, IL-10-/- mice exposed to conventional microbiota presented more severe intestinal inflammation and signs of colitis than IL-10-/- mice maintained under SPF conditions." (PMID 31509557, 2019). "In fact, our results suggest that the transfer the IL-10+ Bregs can effectively suppress inflammation in mice with DSS-induced colitis, indicating that IL-10-producing B cells can reverse the progression of DSS-induced UC." (PMID 29844590, 2019). "To evaluate the anti-inflammatory effects of PWS on DSS + CD-induced colitis, we focused on the pro-inflammatory cytokine IL-1β, and the anti-inflammatory cytokines IL-10 and TGF-β." (PMID 31888274, 2019). "IL-10−/− mice with colitis developed a significant bone defect with reduced trabecular thickness, trabecular number, and bone surface density." (PMID 31847438, 2019). "Exosomes derived from DCs treated with interleukin-10 (IL-10) or transfected with the gene for IL-10 can inhibit trinitrobenzene sulfonic acid (TNBS)-induced rat colitis through stimulating CD4+CD25+Tregs." (PMID 31316512, 2019). "During infection, IL-10 is required to avoid excessive immune response and prevent development of colitis." (PMID 30842764, 2019). "The fact that EPHX2 inhibition appears beneficial in both the DSS and IL10 knockout (KO) colitis models is particularly interesting, since they are driven by very different mechanisms." (PMID 31002701, 2019). "Although IL-10-/- mice were originally reported to spontaneously develop colitis, it has been shown that IL-10-/- mice are resistant to the development of spontaneous colitis when kept in pathogen free environment." (PMID 31534535, 2019). "Together, these in vivo results indicate that PI3Kδ signaling plays a pivotal role in IL-10-producing B cell protection in T cell-mediated colitis." (PMID 31546615, 2019). "Bregs in murine colitis models express CD1d and produce IL-10 to directly suppress intestinal inflammation." (PMID 31474988, 2019).
colitis (continued). "Blimp-1-deficient Tregs cannot suppress the formation of colitis in mice and fail to inhibit CD4+ T cell proliferation, likely owing to their reduced production of IL-10." (PMID 31474988, 2019). "In the present study, 15‐week‐old male Il‐10−/− mice with spontaneous colitis were divided into positive control and Bry‐1‐treated (Bry‐1, 30 μg/kg every other day, injected intraperitoneally for 4 weeks) groups." (PMID 31251471, 2019). "In the present study, we investigated the effects of Bry‐1 on spontaneous CD‐like colitis in Il‐10−/− mice and the possible mechanism of these effects with the hope of providing a new therapeutic option for CD." (PMID 31251471, 2019). "In contrast to Th17 and Th1, regulatory T cells (Treg), which can be defined by expression of Foxp3, are capable of suppressing the activation of Th17 and Th1 cells through the production of IL-10 and transforming growth factor-β in mouse colitis models." (PMID 31921214, 2019). "The inhibition of Gls1 by BPTES significantly increased Gln expression in IL‐10−/− mice and showed a protective effect in experimental colitis." (PMID 31211512, 2019). "Work examining changes in the E. coli commensal transcriptome during intestinal inflammation or colitis in mice found that ybaM mRNAs decreased 2.2-fold in IL10(−/−) mice, those suffering from colonic inflammation, compared to wild type mice." (PMID 30872786, 2019). "Subsequent studies revealed that SPF Il10−/− mice housed at some institutions readily developed extensive colitis, while Il10−/− mice housed at other institutions fail to develop colitis." (PMID 31703321, 2019). "Co-colonization of ASF-colonized Il10−/− mice with segmented filamentous bacteria (SFB) abolished MNV-induced colitis, whereas histopathological scores in SFB-OMM12-co-colonized mice stayed unchanged." (PMID 31396223, 2019). "WT B cells decreased histologic inflammation in a CD4+ and B cell co-transfer colitis model with significantly less protection by either PI3KδD910A or Il10−/− B cells." (PMID 31546615, 2019). "In detail, B cell immunity is inoperative, either due to the lack of mature B cells (Rag1−/−), the disturbed proliferation and induction of Bregs (IL-2−/−), or the dysfunction of Bregs (IL-10−/−) in all three colitis mouse models." (PMID 32038631, 2019). "The finding that IL-10-mediated p38 signaling inhibited TNF-induced recruitment of ATF6 to the Grp78 promoter provides a plausible explanation for colitis development in IL10−/− mice." (PMID 31867005, 2019). "Both MAM and PSA prevented dextran sulfate sodium (DSS)- and 2,4,6-trinitrobenzenesulfonic acid (TNBS)-induced colitis in murine models, reducing Th1, Th17, and Th2 immune responses, and promoting Treg production of IL-10 and TGF-β." (PMID 32010704, 2019). "Then we proceeded with IL-10-/- models in which colitis was induced with TNBS or DSS, and eventually, FVB mice induced with DSS." (PMID 31534535, 2019). "Gnotobiotic IL10−/− mice have been previously used as a model to investigate the colitis-inducing potential of individual bacterial strains, including indigenous strains of E. coli." (PMID 31391483, 2019). "IL-10 signaling during Giardia infection has recently been shown to be important in preventing development of colitis in mice." (PMID 31260452, 2019). "Immunofluorescence microscopy and histochemical assays showed an abundance of macrophages accumulated in the colon of DSS-colitis mice, and a higher number of IL-10-producing cells appeared in the B. adolescentis IF1-03 protection mouse colon sections." (PMID 30987344, 2019). "It has been shown that the exposure of IL-10-/- mice to piroxicam can result in rapid and uniform development of colitis, which persists for a long period of time even after piroxicam is discontinued 22-24." (PMID 31534535, 2019). "In the present study, rBmaCys-treated colitis mice had elevated percentages of CD4+IL-10+ Tregs in LPMCs and CD4+ Tregs in MLNs." (PMID 31683524, 2019).
colitis (continued). "In a clinical setting, administration of macrophages characterized by increased IL-10 secretion attenuates the development of acute sepsis and chronic autoimmune diseases such as colitis." (PMID 31148944, 2019). "Recently, NLRP6 was shown to prevent the colonization of IBD-inducing bacteria, the mucolytic A. muciniphila, which can induce colitis in both specific pathogen free and germ free (GF) IL10−/− mice." (PMID 31139196, 2019). "Remarkable increases in VCAM-1 expression have also been documented in rodent models of chemically induced colitis, as well as in colitis of IL-10 knockout mice." (PMID 31035617, 2019). "It has been suggested that E. faecalis improves colitis by increasing interleukin-10 (IL-10), a factor that inhibits cytokine synthesis, in colonic epithelial cells." (PMID 31672153, 2019). "Inhibition of Gls1 by BPTES maintains the Th/Treg balance, controls inflammatory reactions and maintains intestinal barrier integrity, which ameliorates spontaneous colitis in IL‐10−/− mice." (PMID 31211512, 2019). "LCN-2 knockout mice harbor colitogenic bacteria, and this protein has been reported to reduce intestinal inflammation in the IL-10-knockout model of colitis." (PMID 31311100, 2019). "We colonized germfree, inflammation-susceptible Il10−/− mice with NC101 or the ΔfyuA or Δirp1 mutant and compared the severities of colitis induction." (PMID 31481410, 2019). "Nevertheless, IL-10 plays an important role in suppressing inflammation in mucosa cells evident by IL-10 knockout mice that will develop severe colitis." (PMID 31795299, 2019). "The development of the colitis is associated with the dysregulation of the Treg-TH17 equilibrium and a large decrease in the production of IL-10." (PMID 30992496, 2019). "Blocking VEGFR-3 resulted in a worsened colitis in IL-10 knockout mice as well as DSS-treated animals in terms of the histological score." (PMID 30863410, 2019). "Studies with germfree Il10−/− mice individually colonized with AIEC have led to the identification of several bacterial factors that augment or diminish the colitis-inducing and procarcinogenic capabilities of AIEC (17, –, 20)." (PMID 31481410, 2019). "It is noteworthy that CD4+CD25+ Treg has been shown to prevent and resolve murine colitis, and the cure of murine colitis by these cells was dependent on the presence of IL-10." (PMID 31888063, 2019). "IL-10−/− mice spontaneously develop colitis in which macrophages preferentially differentiated into proinflammatory subsets that produce high levels of IL-12 and IL-23." (PMID 31886308, 2019). "We investigated the role of PI3Kδ signaling in B cell production of IL-10, following stimulation by resident bacteria and B cell regulatory function against colitis." (PMID 31546615, 2019). "According to unpublished data from other groups (Dr. Laura Hale), IL-10-/- mice start to show persistent colitis at day 19 after piroxicam is used in the diet for one week as verified on H&E staining." (PMID 31534535, 2019). "A study showed that NLRP6, an innate immune receptor, is important for suppressing the development of spontaneous colitis in the IL10−/− mouse model of IBD." (PMID 31510015, 2019). "In our study, we first assessed the impact of minimal bacterial consortia alone on colitis development in Il10−/− mice." (PMID 31396223, 2019). "In contrast, significantly lower number of regulatory, IL-10-producing DCs (p < 0.05), which suppressed T cell-driven colon inflammation, was observed in Gal-3−/− animals 28 days after initial DSS administration." (PMID 31336879, 2019). "More recent work using an IL-10-deficient model of spontaneous colitis, or dextran sulfate sodium (DSS) to induce colitis, revealed that host-derived nitrate can directly support a bloom of Enterobacteriaceae bacteria in the colon." (PMID 31138751, 2019).
colitis (continued). "as one of the top ten most abundant genera associated with human colorectal carcinoma and provide experimental evidence that Alistipes potently induces inflammation in colitis-prone Il10−/− mice." (PMID 31578395, 2019). "Il10−/− mice, which lack anti-inflammatory cytokine IL-10 and show spontaneous colitis in a gut microbiota-dependent manner, were used in this study." (PMID 31767028, 2019). "fae consortium developed severe inflammation in the distal colon (score: 4.8 ± 2.4), while the degree of colitis was significantly reduced in IL-10−/− mice colonized with SIHUMI in the presence of E. faecalis (score: 2.8 ± 2.5)." (PMID 31281321, 2019). "For example, capsular polysaccharide A (PSA) of Bacteroides fragilis can be delivered to regulatory T cells (Tregs) to induce interleukin-10 (IL-10) production against experimental colitis." (PMID 31137777, 2019). "For example, commensal Bacteroides fragilis polysaccharide promotes TLR2 dependent development of IL-10 producing Tregs and tolerance in experimental colitis." (PMID 30717413, 2019). "miR-141 overexpression contributes to alleviated experimental colitis in the IL-10 knockout or 2,4,6-trinitrobenzene sulfonic acid-induced chronic colitis mice." (PMID 31383782, 2019). "Patients with genetic defects in the IL-10/IL-10R pathway develop severe early-onset colitis that can be healed by transplanting IL-10/10R-sufficient stem cells." (PMID 31244763, 2019). "ERβ-specific agonists were also indicated to have direct effects on colitis, as suggested by increased IL-10 production in immune cells." (PMID 31226730, 2019). "The colitis that IL10−/− mice develop requires microbial exposure, as GF mice are protected from disease." (PMID 31391483, 2019). "We previously showed that hMSCs alleviated experimental colitis, altered the imbalances of Treg/Th1/Th17 cells, and strikingly increased the number of IL-10-producing CD5+ Breg cells." (PMID 31367246, 2019). "This is also in line with data generated in the IL-10 KO mouse, another model of colitis in which increased small intestinal permeability was shown to have a pathogenetic role in leading to colitis." (PMID 31608059, 2019). "Previous studies have mainly focused on T cells and macrophages to determine the roles of IL-10 in the pathogenesis of IBD, while our work and that of others has demonstrated the importance of IL-10 production by B cells in experimental colitis." (PMID 31546615, 2019). "IL-10 secreted by lamina propria macrophages has been shown to be important for maintaining Foxp3 expression in a mouse model of colitis." (PMID 30987344, 2019). "INF-γ and IL-17 implicated in driving the inflammation in several models of murine colitis and IL-10 inhibited the production of pro-inflammatory mediators such as INF-γ, TNF-α3 and limited the disease." (PMID 31836772, 2019). "T. spiralis ES products were also used to alleviate DSS-induced colitis by inducing Treg expressing IL-10 and TGF-β." (PMID 31703440, 2019). "IL-10 production in colitis mice was significantly higher than control, but this increase was not statistically significant." (PMID 31836772, 2019). "As an example, the tolerogenic responses in the intestine are maintained through the concerted action of interleukin 10 (IL-10)-secreting macrophages and DCs and IL-10 is fundamental in the suppression of inflammation such as colitis." (PMID 30813381, 2019). "The results of our experiments with mice that were treated with antibiotics clearly show that microbiota plays a major role in the progression of colitis in the Il10-/- model." (PMID 31275292, 2019). "In our study, the 2FL-mediated reduction of colitis in the Il10-/- model was accompanied by the outgrowth of R. gnavus." (PMID 31275292, 2019). "The Il10−/− mice are considered the gold standard colitis model that closely recapitulates human IBD." (PMID 30410494, 2018).
colitis (continued). "More importantly, they showed that administration of IL-1βR antagonist to IL-10 KO mice led to an impressive decrease in colitis." (PMID 30455704, 2018). "To examine the direct effect of Bregs in ERC-based therapy, we isolated CD1d+CD5+ Bregs from the spleen of ERC-treated colitis mice to perform adoptive transfer, which is an important IL-10 source." (PMID 29784012, 2018). "Very similar to our results with MCC950 in Winnie mice, glyburide effectively suppressed NLRP3 inflammasome activation in IL-10−/− mice, leading to attenuation and prevention of colitis." (PMID 29872077, 2018). "In the TCRα−/− spontaneous colitis model, B cells protected the colon from severe inflammation by generating CD1d upregulated Bregs capable of producing interleukin (IL)-10." (PMID 29784012, 2018). "β-glucan treatment increased IL-10 production via PPARγ sensing, promoting the attenuation of colitis and C. glabrata elimination." (PMID 30524506, 2018). "A recent report suggested that defective signaling of IL-10, an anti-inflammatory cytokine, in a lipopolysaccharide-induced colitis of mice and in macrophages of IBD patients led to dysregulated activation of the NLRP3 inflammasome and production of IL-1β31." (PMID 29773794, 2018). "Intestinal IL10 expression resulted in a significant reduction in colitis related pathological symptoms and in the severity of intestinal inflammation." (PMID 30374059, 2018). "HD5 treatment blocked these effects of EtOH and colitis and maintained IL-10 and TGFβ mRNA at high levels." (PMID 30389960, 2018). "For example, a Lactococcus lactis strain secreting IL-10 was found to decrease DSS-induced colitis by 50%; however, humans treated with a biocontained strain (thyA-/hIL-10+) did not experience beneficial effects in a phase II-A trial." (PMID 29636738, 2018). "Systemic reconstitution of DKO mice with bone marrow-derived mast cells resulted in significant amelioration of IL10−/−-mediated colitis and intestinal barrier injury." (PMID 29849494, 2018). "In the present study, DKO mice had elevated colonic production of TNF and histologic colitis scores that were restored to IL10−/− levels with systemic reconstitution of DKO mice with BMMCs." (PMID 29849494, 2018). "In experimental colitis, a downregulation of miR-375 expression in IL-10-/- mice once the signs of the colonic inflammation were evident was reported." (PMID 29867475, 2018). "Although IL-10 is known to play a protective role in colitis, we observed a small decrease in IL-10 levels in mice treated with CAPE, which was expected as CAPE is known to lower the levels of IL-10." (PMID 28528363, 2018). "We show that a short period of IL-10 overexpression before the induction of colitis ameliorated the disease outcome, despite the presence of CD11b+ Ly6C+ cells in the gut, previously associated with the development of detrimental inflammation." (PMID 29545807, 2018). "These compounds not only suppress Th17 differentiation and IL-17 production, but also reduce the severity of experimental autoimmune diseases including the IL10−/− model of colitis." (PMID 30405600, 2018). "This endoscopic system was able to detect polypoid, intraepithelial flat lesions, colitis, and lymphoid aggregations in vivo, in a colitis mouse model (IL10-/- Piroxicam)." (PMID 30388158, 2018). "Taken together, these data indicated that CD69+ Tregs suppressed chemical-induced colitis in a IL-10 dependent manner." (PMID 30185773, 2018). "IL-10−/− mice and IL-10−/−;T-Hk2−/− mice both developed mild colitis marked by lymphocytic infiltrate in the colon, a failure to gain weight, splenomegaly, and rectal prolapse." (PMID 30140438, 2018). "Further, these findings suggest that B. fragilis is involved in a distinct preventive mechanism against intestinal inflammation in carcinogen/DSS-induced CRC compared to regulation by IL-10 or Foxp3 in T-cell transfer or a TNBS colitis model." (PMID 30429227, 2018).